ASF1B (anti-silencing function 1B histone chaperone)
Diseases named in the same sentence as ASF1B in open-access papers (continued):
Sharing a sentence is not in itself a finding about the gene and the disease.
adenocarcinoma (1 paper, 2024). A common cancer characterized by the presence of malignant glandular cells. "The present results also exhibit that among the amplified genes, the following eight genes involved in the cell cycle were found to be amplified in more than 5% of HGSO adenocarcinoma patients: ATAD2, ASF1B, CCNE1, CDC20, CDCA8, RECQL4, RNASEH2A, and SMC4." (PMID 39199556, 2024).
ASF1B also shares sentences with these, for which no sentence is quoted: esophageal cancer (3 papers); glioblastoma (3); colon adenocarcinoma (2); Kidney Chromophobe (2); Lung squamous cell carcinoma (2); mesothelioma (2); rectal cancer (2); rectum adenocarcinoma (2); sarcoma (2); thymoma (2); acute lymphoblastic leukemia (1); anemia (1); B-cell acute lymphoblastic leukemia (1); bile duct cancer (1); bladder cancer (1); Burkitt lymphoma (1); B‐cell lymphomas (1); cervical squamous cell carcinoma (1); cholangiocarcinoma (1); endocervical adenocarcinoma (1); head and neck cancer (1); head and neck squamous cell carcinoma (1); hemoglobinopathies (1); kidney cancer (1); leukemia (1); lymphoma (1); neutropenia (1); osteosarcoma (1); ovarian serous cystadenocarcinoma (1); Pan (1).
A further 10 diseases each share a sentence with ASF1B in 1 paper.